GPX3 (glutathione peroxidase 3)
Diseases named in the same sentence as GPX3 in open-access papers (continued):
Sharing a sentence is not in itself a finding about the gene and the disease.
gastric cancer (continued). "Low expression of GPX3 is closely related to the occurrence, development, and prognosis of tumors such as gastric cancer." (PMID 39132501, 2024). "Next, to further validate the roles of FIRGs in the development of gastric cancer, we silenced GPX3, SPARC and NOX4 in gastric cancer cell lines MGC803 and MKN45 to examine the effects on the cell viability, proliferation and migration/invasion." (PMID 38021154, 2023). "We found that GPX3 expression levels were high in ovarian and renal clear cell carcinoma and moderate in breast, colorectal, and gastric cancers." (PMID 36845676, 2023). "Breast, ovarian, colon, and gastric cancer cells were used to investigate the relationship between GPX3 expression and cancer cell metastasis, proliferation, and chemotherapy sensitivity." (PMID 36845676, 2023). "We compared GPX3 expression levels in ovarian cancer, renal clear cell carcinoma, breast cancer, colorectal cancer, and gastric cancer cell lines using the CCLE database." (PMID 36845676, 2023). "It was found that 60 percent of stomach cancer samples exhibited DNA hypermethylation after analyzing the GPX3 promoter (P=0.007) (a methylation level of more than 10 percent, as measured by bisulfite pyrosequencing)." (PMID 35069731, 2022). "More study is needed to determine if GPX3 contributes to the onset, progression, or metastasis of gastric cancer." (PMID 35069731, 2022). "GPX3 is a tumor suppressor that prevents migration and invasion through the Wnt pathway in gastric cancer." (PMID 35740301, 2022). "According to the research, GPX3 expression was decreased or silenced in eight of nine cancer cell lines and 83 percent of gastric cancer samples (90/108) as compared to normal gastric tissues in the vicinity of the tumor (P < 0.0001)." (PMID 35069731, 2022). "Compared to normal tissues and cells, Gpx3 expression was lower in gastric cancer (GC) patients and GC cell lines." (PMID 36199800, 2022). "The effects of DNA hypermethylation on GPX3 transcriptional regulation were examined using the gastric cancer cell lines SNU1 and MKN28." (PMID 35069731, 2022). "In the end, we screened out 3 molecules, GPC3, GPX3 and PRICKLE1, and constructed a risk scoring model for gastric cancer samples." (PMID 34926458, 2021). "In patients with stomach cancers, GPX3, CLEC3B, CFD, GSN, and CCL14 were the leading five genes that were most significantly downregulated." (PMID 33828156, 2021). "In contrast, GPX3 expression was shown to be lower in gastric cancer patients compared to the normal tissues, and the overexpression of GPX3 can inhibit gastric cancer cell migration and invasion." (PMID 33596182, 2021). "In gastric cancer, decreased expression of GPX3 was reported as s a poor prognosticator, and GPX3 expression is mediated by genetic and epigenetic alterations caused by promoter hypermethylation." (PMID 32316597, 2020). "Based on our results and earlier reports, we suggest that downregulation of GPX7 and GPX3 denotes a severe dysfunctional antioxidant system in gastric cancer cells." (PMID 28903346, 2017). "A number of studies have shown that GPX-3 levels are decreased in women with papillary serous ovarian cancer in a stage-dependent manner and also found decrease in women with gastric cancer." (PMID 27803713, 2016). "Hypermethylation of the GPX3 promoter (≥10%) was detected in 60% (36/60) of the gastric cancers and 6/9 cancer cell lines, consistent with our results showing GPX3 downregulation." (PMID 23071548, 2012). "Further studies to explore the functions of GPX3 in gastric tumorigenesis are required to address its potential role in the development and progression of gastric cancer, in particular, its potential roles in tumor cell migration and metastasis." (PMID 23071548, 2012). "There was a significantly lower level of GPX3 DNA copy numbers in the gastric cancers and the tumor-adjacent “normal" stomach tissue samples, as compared to that in normal blood samples (P = 0.001)." (PMID 23071548, 2012).
gastric cancer (continued). "To study the expression and gene regulation of GPX3, we examined GPX3 gene expression in 9 gastric cancer cell lines, 108 primary gastric cancer samples and 45 normal gastric mucosa adjacent to cancers using quantitative real-time RT-PCR." (PMID 23071548, 2012). "In the present study, we examined GPX3 gene expression, gene promoter methylation status, and copy number in a panel of primary gastric cancers and correlated it with clinicopathological parameters." (PMID 23071548, 2012). "Taken together, the dysfunction of GPX3 in gastric cancer is mediated by genetic and epigenetic alterations, suggesting impairment of mechanisms that regulate ROS and its possible involvement in gastric tumorigenesis and metastasis." (PMID 23071548, 2012). "The average methylation level for the GPX3 gene promoter in gastric cancers was significantly higher than that in normal samples (P = 0.007)." (PMID 23071548, 2012). "The qRT-PCR analysis demonstrated that GPX3 mRNA expression was frequently downregulated in gastric cancer cell lines (8/9 cell lines examined) and in primary gastric cancer tissue samples (90/108, 83%) as compared to 45 normal samples (P<.0001)." (PMID 23071548, 2012). "Examination of GPX3 promoter demonstrated DNA hypermethylation (≥10% methylation level determined by Bisulfite Pyrosequencing) in 6 of 9 cancer cell lines and 60% of gastric cancer samples (P = 0.007)." (PMID 23071548, 2012). "Serum levels of GPX3 have been found to be reduced in various cancers including prostrate, thyroid, colorectal, breast and gastric cancers." (PMID 22017790, 2011). "Knockdown of GPX3 in gastric cancer was shown to result in tumor cell invasion and migration." (PMID 38962317, 2024). "GPX3 inhibited the migration and invasion of gastric cancer cells." (PMID 36845676, 2023). "Genetic and epigenetic alterations lead GPX3 to be dysfunctional in gastric cancer." (PMID 35069731, 2022). "However, a tumor suppressive role also been reported for GPX3 in gastric cancer wherein its knockdown resulted in tumor cell invasion and migration by targeting NFкB/Wnt5a/JNK signaling." (PMID 36389725, 2022). "A new research shows that GPX3 inhibits the growth and spread of stomach cancer." (PMID 35069731, 2022). "Meanwhile, another recent study used the The Cancer Genomic Atlas data to show that GPX3 was hypermethylated in gastric cancer, which may consequently increase the possibility of tumor recurrence." (PMID 33596182, 2021). "Furthermore, an in vitro study an association between GPX3 and lymph node metastasis was found in gastric cancer upon downregulation of GPX3 expression and promoter hypermethylation." (PMID 30143675, 2018). "Although GPX3 promoter hypermethylation correlated statistically with low gene expression levels, we detected silencing of GPX3 mRNA expression in 83% (90/108) of gastric cancers, whereas promoter hypermethylation was seen in only 60% (36/60) of gastric cancers." (PMID 23071548, 2012). "DNA copy number, methylation level and gene expression of GPX3 in gastric cancer cell lines." (PMID 23071548, 2012). "Like GPx1, GPx3 exhibits a dual role in cancer, and these seemingly contradictory results may be closely related to ROS; it serves as a pro-survival protein in myeloid leukemia and as a tumor suppressor in lung, ovarian, and gastric cancers." (PMID 39125992, 2024). "We compared the effect of GPX3 on platinum-based chemotherapy sensitivity in several types of cancer cells, and the results showed that shGPX3 resulted in increased sensitivity to platinum-based chemotherapy in breast cancer, ovarian cancer, colorectal cancer, and gastric cancer." (PMID 36845676, 2023). "So the goal of this research is to find out whether methylation of the gastric cancer gene GPX3 may be utilized as a prognostic biomarker after radical gastrectomy in 118 Chinese patients with gastric cancer who underwent a quantitative MSP methylation (qMSP) test." (PMID 35069731, 2022).
gastric cancer (continued). "However, the functional research of GPx3 in gastric cancer needs to be further explored." (PMID 34926458, 2021). "GPC3, GPX3 and PRICKLE1 were the candidate sites selected in the risk prediction model for OS, which indicated that the genes might have potential roles on the malignant behaviors of gastric cancer." (PMID 34926458, 2021). "In pancreatic adenocarcinoma, GPx3 represses cell proliferation, which regulates the JNK/c-Jun signaling pathway, and it suppresses metastasis in gastric cancer and prevents migration and invasion by targeting NFкB/Wnt5a/JNK signaling." (PMID 39125992, 2024). "RGS2, GJA1, GPX3, and LOX were less expressed in gastric cancer tissues than in paracancerous tissues (P<0.05)." (PMID 39132501, 2024). "Then, we used RT-PCR and WB to test GPX3 expression levels in ovarian cancer (Ovcar-4), breast cancer (MDA-MB-231, BT-549), colorectal cancer (Lovo, SW480) and gastric cancer (MKN45) cell lines were examined." (PMID 36845676, 2023). "We found that downregulation of GPX3 expression inhibited metastasis in breast cancer (MDA-MB-231, BT-549), colorectal cancer (Lovo, SW480), gastric cancer (MKN45), and ovarian cancer (Ovcar-4)." (PMID 36845676, 2023). "GPX3 acted as one of the eight NRGPI oncogenic driver genes and had been validated in gastric cancer cell lines and clinical samples." (PMID 36845676, 2023). "These molecular characteristics were mainly driven by the eight NRGPI oncogenes (CYTL1, PLCL1, CNTN1, GRP, APOD, GPX3, FCN1, SERPINE1) as validated in the gastric cancer cell lines and clinical samples." (PMID 36389725, 2022). "Among most downregulated genes we found GPX3, PTGER3 and LIPF (−47.5 and −435.63 of fold change for Diffuse and Intestinal tumors respectively), that resulted hypermethylated in gastric cancer." (PMID 34012923, 2021). "Intersection genes TREM2, CTHRC1, BGN, NOX4, GPX3, HEYL, and SFRP4 from the GSE72305 and GSE103236 datasets, which were differentially expressed in the normal gastric mucosa than in gastric cancer cells and in lymph node free to lymph node metastatic GC." (PMID 33976737, 2021). "In our previous study, we reported that GPX3, a secreted form of the GPX family that is readily detectable in plasma and mucosal surfaces, is significantly downregulated in gastric cancers." (PMID 28903346, 2017). "UGT1A1, GPX3, ADH1B, and ADH4 can serve as cross pathway regulatory nodes and can be integrated into a “metabolic immune prognostic model” in the future to optimize precision treatment strategies for gastric cancer." (PMID 41031088, 2025). "Downregulating GPX3 expression slowed the proliferation rate of ovarian cancer (Ovcar-4) and colorectal cancer (Lovo, SW480) cells but did not significantly affect the proliferation of breast cancer or gastric cancer cells." (PMID 36845676, 2023). "Downregulation or silencing of GPX3 was detected in 8 of 9 cancer cell lines, 83% (90/108) gastric cancers samples, as compared to non-tumor adjacent normal gastric samples (P<0.0001)." (PMID 23071548, 2012). "Unfortunately, we did not confirm the similar tumor suppression role of GPX3 in two gastric cancer cell lines (AGS and MKN28), suggesting that GPX3 may have differential functional roles in different organs." (PMID 23071548, 2012). "We transfected GPX3 knockout adenovirus (shGPX3), GPX3 overexpression adenovirus (oeGPX3), and corresponding control (Ctrl) into breast cancer (MDA-MB-231, BT-549), colorectal cancer (Lovo, SW480), gastric cancer (MKN45), and ovarian cancer (Ovcar-4) cell lines." (PMID 36845676, 2023). "There were varying views on whether or not abnormal GPX3 methylation and expression were present in gastric cancer, but it was generally agreed upon that they were." (PMID 35069731, 2022). "However, there is still no convincing evidence linking GPX3 methylation to a better prognosis in patients with gastric cancer at this point." (PMID 35069731, 2022).
gastric cancer (continued). "All genes except GPX3, ZBTB16, and KCNQ1 have OR of >1 for gastric cancer, whereas all genes have OR of >1 for Parkinson’s disease, suggesting that for a patient who has either Parkinson’s disease or gastric cancer, the status of 12 genes is highly likely to be un-silenced." (PMID 33596182, 2021). "Moreover, about one-third (36/108, 33%) of primary gastric cancers and 6/9 of the cancer cell lines showed complete silencing of GPX3 mRNA expression, as indicated by the absence of a detectable signal." (PMID 23071548, 2012). "However, some studies have found that GPX3 has no antitumor effect in AGS and MKN28 gastric cancer cell lines." (PMID 36845676, 2023). "Tumor suppression in Gpx3 was absent in two additional gastric cancer cell lines (AGS and MKN28), indicating that Gpx3 may have a distinct function in other organs." (PMID 35069731, 2022).
Obesity (28 papers, 2010 to 2025). Accumulation of substantial excess body fat. "GPX3 has been associated with insulin receptor downregulation in white adipose tissue in obese insulin-resistant mouse models and in humans with obesity." (PMID 35511873, 2022). "The other four haplotypes were associated with obesity when classification was based on BFP—one of them in GPX3 in a protective direction and the others in PON genes." (PMID 32752212, 2020). "Too much data regarding the association between obesity and GPx1, GPx3, GPx4, and GPx7 has been reported." (PMID 29132311, 2017). "Discrepancies in ethnicity, concurrent pharmacotherapy and dietary patterns within human cohorts may underpin the diverse associations between GPX3, obesity, and T2D." (PMID 38927092, 2024). "Importantly, both loci showed protection against obesity: GPX3 rs922429 T allele and GPX4 rs2074451 T allele." (PMID 32752212, 2020). "In addition, we found two polymorphisms the GPX4 rs2074451 and GPX3 rs922429 significantly and marginally associated with obesity by PBF respectively." (PMID 32752212, 2020). "Similarly, obesity is also associated with a reduction of Glutathione Peroxidase 3(GPx3) activity in adipose tissue." (PMID 33015130, 2020). "GPX3 might be an important mediator of estrogen effects in relation to fat accumulation because GPX3 levels are lower in obesity and higher after weight loss." (PMID 22163294, 2011). "Indeed, in a recent study of animal models, a combination of hyperglycemia, long-term insulin resistance and obesity was linked to reduced mRNA expression of thioredoxin reductase 3 (Txnrd3) along with selenoprotein Gpx3 and selenophosphate synthetase 2 (Sephs2) in adipose tissue." (PMID 35328380, 2022). "Moreover, an association between obesity and reduced expression of GPx3 has been demonstrated." (PMID 32131476, 2020). "Similarly, Gpx3 (p = 5 × 10−12 by 3SEQ, p = 6.6 × 10−4 by qPCR), a glutathione peroxidase, is an antioxidant enzyme that acts in fat and glucose metabolism and has been associated with obesity and type 2 diabetes in mouse and human." (PMID 25871848, 2015). "GPX3 rs922429 was shown to protect against obesity according to body fat percentage in a study in Mexico." (PMID 38927092, 2024). "HFD-induced obesity lowers the GPX3 plasma concentration in mice and GPX1 expression in the liver and reduces serum glutathione." (PMID 36831188, 2023). "Recently, interest has grown around the implication of GPx3 in obesity and IR, identifying GPx3 as a potentially novel regulator of IRS-1 expression and insulin sensitivity in WAT." (PMID 36079831, 2022). "To confirm the link between the selenoprotein GPX3 and obesity and insulin resistance, we analyzed this cohort of obese patients in more detail." (PMID 35624726, 2022). "DCE prevented the changes in the gene expression of GSR, PGC-1α and NOX-4 (p < 0.05 for all) induced by obesity and also increased the mRNA levels of GPX-3 (p < 0.05)." (PMID 36139877, 2022). "GPX3 deficiency has been associated with inflammatory bowel disease, DM2, obesity, and cardiovascular disease." (PMID 34545296, 2021). "In this study we found six haplotypes associated with obesity, two of them (one in GPX3 and the other in GPX5 and GPX6) when obesity was classified by BMI." (PMID 32752212, 2020). "We found two haplotypes associated with obesity by BMI (in GPX3 and in GPX5 and GPX6) and five haplotypes associated with obesity by PBF (in GPX3, in PON1, and in PON2 and PON3)." (PMID 32752212, 2020). "GPX3, GHR and SAA1 were removed from further study because they have been reported previously to be associated with obesity." (PMID 33318306, 2020). "We found six haplotypes associated with obesity—two of them (one in GPX3 and the other in GPX5 and GPX6) in a protective direction when obesity was classified by BMI." (PMID 32752212, 2020).